DNMT3A (DNA methyltransferase 3 alpha)
Diseases named in the same sentence as DNMT3A in open-access papers (continued):
Sharing a sentence is not in itself a finding about the gene and the disease.
lung carcinoma (continued). "The data uncovered that DNMT3A might act as a TSG, and its suppression might result in the progression of lung cancer." (PMID 36091786, 2022). "Thus, DNMT3A plays a pivotal role in modulating tumorigenesis through activating the PI3K/AKT pathway in liver cancer and lung cancer." (PMID 34148029, 2021). "DNMT1/3A/3B were positively related with PLK1/4 in lung cancer subtypes, except the correlation between DNMT3A and PLK1 without significance in lung squamous cell carcinoma." (PMID 34080290, 2021). "G9a HMTase activity was linked to cancer stemness in lung carcinoma by maintaining oncogenic DNA methylation patterns via interaction with DNMT1, but not DNMT3A." (PMID 33323965, 2021). "For example, the expression level of miR-29s was found to be inversely correlated with DNA methyltransferase 3A (DNMT3A) and DNA methyltransferase 3B (DNMT3B) in lung cancer tissues by controlling methylation to inhibit the reexpression of tumor suppressor genes and inhibit tumorigenesis." (PMID 34789236, 2021). "While in the presence of miR-101, the expression of DNMT1 and DNMT3B did not change significantly, indicating that DNMT3A is a direct target of the miR-101 in lung cancer cells." (PMID 32751889, 2020). "In our study, the final fall in expression of de novo Dnmt3a and Dnmt3b could be explained by the recent demonstration of downregulation after induction of EMT by TGFβ in lung cancer cells." (PMID 27129173, 2016). "Conditional deletion of DNMT3A in mice promotes growth and progression, but not initiation, of lung tumor and leads to global hypomethylation in lung cancer." (PMID 27462454, 2016). "In addition to a previous study that reported that the miR-29 family regulated both DNMT3A and DNMT3B in lung cancer, in this study we showed that DNMT3A is regulated by miR-143 in CRC." (PMID 19638978, 2009). "Interestingly it was shown that hsa-mir-29c directly targets DNA-methyl transferase 3A (DNMT3A) and 3B (DNMT3B) in lung cancer tissue." (PMID 18493317, 2008). "Therefore, DNMT3A may participate in the suppression of NSCLC in human, which was consistent with the finding from previous study in mouse model with lung cancer." (PMID 28423585, 2017). "In another study, when the level of DNMT1, DNMT3A and -3B in lung cancer cell lines were normalized against PCNA, no over-expression of DNMTs were observed, suggesting overexpression of some of these genes may be a reflection of increased cell proliferation." (PMID 20119531, 2009). "Furthermore, abnormal activation of DNMT3A and DNMT3B is closely related to the early occurrence of lung cancer, and their inhibitors (such as azacitidine and decitabine) have been approved for use in hematological tumors and are being explored for epigenetic therapy in lung cancer." (PMID 41394878, 2025).
myelodysplastic syndrome (80 papers, 2011 to 2026). A clonal hematopoietic disorder characterized by dysplasia and ineffective hematopoiesis in one or more of the hematopoietic cell lines. "Summary of the clinicopathologic features of DNMT3A (R882 vs. Non-R882) mutations in myelodysplastic syndromes." (PMID 35296003, 2022). "Later, recurrent DNMT3A mutations have been identified in other types of cancers, including myelodysplastic syndrome (MDS) and T-cell lymphomas (reviews)." (PMID 30185810, 2018). "Mutations in DNMT3A are uncommon in neoplastic conditions other than certain leukemias and myelodysplastic syndrome." (PMID 28503201, 2017). "Frequent mutations in DNMT3A have been demonstrated in human T cell lymphoma, myelodysplastic syndromes, as well as myeloid and monocytic leukemias." (PMID 23666104, 2013). "DNMT3A mutations were also identified in 8% of patients with myelodysplastic syndrome." (PMID 24667323, 2014). "DNMT3A mutations have also been described, albeit at lower frequency, in other myeloid malignancies, such as myelodysplastic syndromes (MDS; 3%–8%) and myeloproliferative neoplasms (MPNs; 2%–10%), as well as early T-cell precursor acute lymphoblastic leukemia (ETP-ALL; 16%–18%)." (PMID 24622842, 2014). "Early studies suggest that DNMT3A mutations are involved in hematological malignancies such as myelodysplastic syndrome (MDS), adult early T-cell precursor acute lymphoblastic leukemia (ETP-ALL), and AML." (PMID 38807916, 2024). "The carriers of somatic PIGA and BCOR/BCORL1 mutations show a lower risk of AA transformation to myelodysplastic syndrome (MDS), whereas myeloid driver lesions such as DNMT3A and ASXL1 mutations characterize the group with a higher risk of malignancy." (PMID 38646536, 2024). "However, compared with conventional myelodysplastic syndromes, these cases displayed a paucity of somatic mutations in DNMT3A (2 of 41) and TET2 (3 of 41 cases), suggesting that evolutionary paths may differ between cases with long versus short telomeres." (PMID 35835912, 2022). "DNMT3A mutations have also been reported in myelodysplastic syndromes (MDS), chronic myelomonocytic leukaemia (CMML), and myeloproliferative neoplasms (MPN)." (PMID 34968247, 2021). "The concomitant presence of other mutations, such as those involving the DNMT3A or TET2 genes, known for their association with myelodysplastic syndromes or expanded hematopoietic clones, has been found in up to 24% of VEXAS cases." (PMID 40046741, 2025). "Significant sex differences exist in the genomic aberrations underlying disease pathology, including a higher prevalence of SF3B1, SRSF2, and ASXL1 mutations in males and DNMT3A mutations in females with clonal hematopoiesis indeterminate potential and myelodysplastic syndromes (MDS)." (PMID 39402216, 2024). "Case LYWS-1389 (Erica Swenson) had a concurrent diagnosis of myelodysplastic syndrome (MDS) and AITL with a shared TET2 mutation, and with DNMT3A and RHOA mutations additionally identified only in the AITL component involving the pleural fluid." (PMID 37500795, 2023).
myelodysplastic syndrome (continued). "DNMT3A mutations and deletions have been analyzed in AML, chronic myeloid leukemia (CML), chronic myelomonocytic leukemia (CMML), myelodysplastic syndrome (MDS), lymphoma and myeloproliferative neoplasms (MPNs)." (PMID 23946816, 2013). "We report a 65-year-old patient with heavily pretreated, FRα-positive ovarian cancer who developed therapy-related myelodysplastic syndrome with increased blasts (MDS-IB2, DNMT3A-mutated) during therapy with MIRV in combination with carboplatin having received prior PARPi maintenance therapy." (PMID 42088210, 2026). "It is possible that the methylation profile varies according to the hematologic malignancy, as observed in myelodysplastic syndrome, where a hypomethylated profile was detected in intragenic regions of DNMT3A in bone marrow cells compared to healthy individuals." (PMID 37372315, 2023). "In myelodysplastic syndromes, 57% of patients had DNMT3A aberrant gene body hypomethylation." (PMID 36443876, 2022). "Mutations of DNMT3A are frequently observed in different hematological malignancies, including AML (both adult and pediatric), T-cell acute lymphoblastic leukemia (T-ALL), myelodysplastic syndrome (MDS), and T-cell lymphomas (TCL)." (PMID 36059621, 2022). "Somatic mutations of DNMT3A result in aberrant DNA methylation, disrupting normal hematopoietic stem cell (HSC) differentiation and self-renewal, and are associated with adverse overall survival (OS) in AML and myelodysplastic syndrome (MDS) patients." (PMID 35296003, 2022). "In these patients, the risk of direct evolution of DNMT3A–clonal hematopoiesis to donor cell leukemia (DCL) is low, and most DCLs were traced to atypical donor clonal hematopoiesis involving myelodysplastic syndrome–associated (MDS-associated) genes or germline risk alleles." (PMID 35608905, 2022). "Of these non-JAK2 mutation cases, the NRAS, CSF3R and TET2 c.4319_4329del; p.Arg1440Hisfs*34 were in the context of therapy-related disease; the remaining 4 other mutations (TET2, TET2, DNMT3A, and SF3B1) were in the context of disease progression from myelodysplastic syndrome." (PMID 36323674, 2022). "The variant allele fraction (VAF) of DNMT3A mutations in patients with T-ALL was consistently ∼50%, suggestive of heterozygous mutations found in all the tumor cells, presenting DNMT3A mutation as a founding event in T-ALL as in AML23 and myelodysplastic syndromes." (PMID 40552132, 2024). "The most frequent DNMT3A hot-spot mutation R882H was observed in up to 60% of AML, 18% of ALL, and 10% of myelodysplastic syndrome (MDS) patients." (PMID 36614080, 2022). "Hematopoietic-specific conditional Dnmt3a knockout mice develop a myelodysplastic syndrome (MDS) or MPN phenotype in mice." (PMID 34944812, 2021). "Driver mutations, such as DNMT3A, TET2, and ASXL1, appear early in AML clones and in the myelodysplastic syndrome (MDS)." (PMID 33363031, 2020). "DNMT3A is one of the most frequently mutated DNA methyltransferase in AML and myelodysplastic syndromes (MDS)." (PMID 30984620, 2019). "Genes that regulate DNA methylation and demethylation (e.g., DNMT3A, IDH1 and IDH2, TET2) are commonly mutated in adult AML and myelodysplastic syndromes (MDS), although the frequency of these mutations appears much lower in pediatric AML." (PMID 24672775, 2014). "Mutations in tet methylcytosine dioxygenase 2 (TET2) and DNA methyltransferase 3 alpha (DNMT3A) in AML and myelodysplastic syndrome lead to either hypermethylation or hypomethylation of enhancers, thereby affecting the accessibility of specific TFBS." (PMID 40032852, 2025). "Moreover, patients with myelodysplastic syndrome (MDS) aged > 65 years and harboring TET2, DNMT3A, and AXSL1 mutations were susceptible to PAD and systemic inflammation." (PMID 34943774, 2021). "Recurrent DNMT3A muations have also been identified in myelodysplastic syndrome (MDS)." (PMID 22066015, 2011).
myelodysplastic syndrome (continued). "Unlike DNMT1, somatic mutations in DNMT3A are prevalent in hematologic malignancies of myeloid and lymphoid lineage, including AML (~20%) and myelodysplastic syndromes (MDS; ~10%), and these mutations are associated with a poor prognosis." (PMID 36675240, 2023). "Of 2926 cases with a myeloid NGS test performed, 79 patients with DNMT3A mutant MNs were identified, including 40 (51%) AML, 28 (35%) MDS, 3 (4%) MDS/MPN (myelodysplastic syndrome/myeloproliferative neoplasm), and 8 (10%) MPN." (PMID 35296003, 2022). "In myelodysplastic syndrome (MDS), 5-Aza-CdR can re-activate the expression of the p15INK4B gene in MUTZ-1 cells by demethylation of the p15INK4B gene through inhibition of DNMT3a gene expression which is a mechanism of 5-Aza-CdR in the treatments of MDS." (PMID 34319031, 2021). "Differently from myelodysplastic syndrome (MDS), their efficacy in AML is independent of the mutational status of epigenetic modifiers such as IDH1, IDH2, DNMT3A and TET2." (PMID 34439275, 2021).
myeloid neoplasm (74 papers, 2011 to 2025). Proliferation of myeloid cells originating from a primitive stem cell. "The most frequent mutation, DNMT3A R882, disrupts the enzyme’s ability to effectively methylate DNA, leading to the development and progression of myeloid malignancies by affecting the expression of genes involved in cell differentiation and proliferation." (PMID 40374809, 2025). "NGS is essential for this diagnosis, as it enables detection of at least one somatic mutation in genes commonly mutated in myeloid neoplasms (e.g., DNMT3A, TET2, ASXL1, SF3B1, SRSF2, etc.)." (PMID 41464583, 2025). "While DNMT3B mutations are rarely detected in hematopoietic malignancies, DNMT3A mutations are very common in patients with clonal hematopoiesis and/or myeloid malignancies, and also cause the DNMT3A overgrowth syndrome (DOS)." (PMID 38295174, 2024). "DNMT3A is one DNA methyltransferase needed for de novo methylation throughout the genome: according to reports, 8–22% of myeloid neoplasms and 33% of PTCLs have DNMT3A mutations, which mostly affect the enzyme’s catalytic function." (PMID 38792976, 2024). "DNA methyl transferase 3A (DNMT3A) is one of the most frequently mutated genes in patients with myeloid malignancies." (PMID 36976647, 2023). "Demographics and disease presentation of myeloid neoplasms with DNMT3A (R882 vs. Non-R882) mutations." (PMID 35296003, 2022). "Patients with overt myeloid malignancies showed higher mutation numbers and allele frequencies and a shifting mutation landscape, notably characterized by increasing prevalence of DNMT3A codon R882 variants." (PMID 36131041, 2022). "In general, the presence of DNMT3A mutations in patients with myeloid malignancies has been associated with a higher number of blasts in BM and greater leukocyte counts in blood in the absence of a clear prognostic impact." (PMID 35626091, 2022). "DNMT3A mutations frequently occur in myeloid tumors but are less common in lymphoid malignancies that are mainly found in T-cell lineage diseases." (PMID 35280829, 2022). "DNMT3A mutation was shown to be associated with response to decitabine and azacytidine therapy in myeloid malignancies, and TET2 mutation was associated with the objective response to these DNMT inhibitors in MDS." (PMID 34039392, 2021). "Other co-mutations often seen in myeloid neoplasms with germline RUNX1 are in DNMT3A, FLT3, GATA2, PHF6 (PHD finger protein 6), BCOR (BCL6 Corepressor), WT1, and TET2." (PMID 35054439, 2021). "The genetic profile of these MYC- translocated T-ALL is characterized by concomitant abnormalities, including CDKN2A/B deletions, PTEN inactivation, and mutations typical of myeloid neoplasms, such as DNMT3A." (PMID 32185137, 2020). "Next-generation sequencing (NGS) is used to detect and monitor clonal hematopoiesis, and the spectrum of mutations substantially overlaps with that of myeloid neoplasms with DNMT3A, TET2, ASXL1, and JAK2 being the most frequently mutated." (PMID 32825226, 2020). "DNA methyltransferase 3A (DNMT3A) is mutated in various myeloid neoplasms including AML, especially at the Arg882." (PMID 32015320, 2020). "The presence of a DNMT3A mutation in myeloid malignancies has also been shown to predict a higher likelihood of responding to an HMA." (PMID 31963585, 2020). "Genes associated with methylation and myeloid neoplasms, including DNMT3A and NRAS, were more commonly mutated in T-ALL with CDKN2B hypermethylation." (PMID 30635552, 2019). "TET2 and DNMT3A mutations are commonly found in clonal haematopoiesis and myeloid neoplasms." (PMID 35064935, 2022).
myeloid neoplasm (continued). "Whole exome sequencing and next-generation sequencing in patients demonstrate cooccurrence of FLT3ITD, TET2, and DNMT3A mutations in patients with lymphoid and myeloid malignancies; however, it is unclear how these mutations cooperate and contribute to transformation and poor overall survival." (PMID 36073548, 2022). "Given that DNMT3A mutations often occurred early in the development of myeloid neoplasm and rarely acquired during disease progression, this result suggests that CHIP harboring R882 mutations has a higher risk of developing AML than non-R882 mutations (about 5-fold)." (PMID 35296003, 2022). "Recent studies provide hope for future therapeutic strategies that may address loss-of-function mutations in both the TET2 and DNMT3A genes in cases of myeloid malignancies, and potentially even CHIP and comorbid diseases." (PMID 31963585, 2020). "In this review, we will discuss the current understanding of pre-leukemic biology in myeloid malignancies, and how mutations in two key epigenetic regulators, DNMT3A and TET2, may contribute to disease pathogenesis." (PMID 27597933, 2016). "Especially, loss-of-function mutations in DNMT3A and TET2 are prevalent in clonal hematopoiesis and myeloid neoplasms, including MDS." (PMID 40929300, 2025). "Of note, TET2, IDH2 and DNMT3A mutations are recurrent in myeloid malignancies, while TET2 and DNMT3A mutations are described in clonal haematopoiesis of indeterminate potential." (PMID 40724970, 2025). "Myeloid malignancies were diagnosed in 3 of 5 patients with ASXL1 variants, 1 of 4 with TET2 variants, and 0 of 3 patients with DNMT3A variants." (PMID 40179146, 2025). "Like DNMT3A, TET2 mutations are associated with an adverse clinical outcome in a context-dependent manner in various myeloid neoplasms." (PMID 40374809, 2025). "Certain m5C‐related genes, such as DNA methyltransferase 3 alpha (DNMT3A) and Tet methylcytosine dioxygenase 2 (TET2), frequently mutated in myeloid malignancies and are also associated with an increased risk of neurodegenerative disorders." (PMID 39691424, 2024). "Of note, ARCH is characterized by the presence of somatic mutations in genes that are also frequently mutated in SM (e.g., ASXL1, DNMT3A, EZH2, RUNX1, SF3B1, SRSF2 and TET2) and other myeloid neoplasms." (PMID 35626091, 2022). "Recent studies have revealed that somatic mutations are detected in approximately 30% of AA patients, and mutations in several genes such as DNMT3A, ASXL1, and RUNX1 are associated with secondary myeloid malignancies." (PMID 36467821, 2022). "the median VAF of non-DNMT3A clones increased from 1% at the time of autologous stem cell transplantation (ASCT) to 37% at the diagnosis of therapy-related myeloid neoplasms (tMNs)." (PMID 36465410, 2022). "A share of TN MPNs discloses variants of myeloid neoplasm-/CHIP-associated genes (i.e., DNMT3A, TET2, and ASXL1) with ascertained or putative pathogenicity." (PMID 34830822, 2021). "For the development of myeloid neoplasms, additional mutations beyond CH-associated TET2 and DNMT3A mutations drive further clonal expansion from CH." (PMID 34581268, 2021). "Other genes commonly mutated in myeloid neoplasms, such as FLT3 (fms like tyrosine kinase 3), DNMT3A (DNA Methyltransferase 3 Alpha), IDH1/2 (Isocitrate Dehydrogenase (NADP(+)) 1/2), NPM1 (Nucleophosmin 1), and RUNX1, are rare and almost mutually exclusive." (PMID 35054439, 2021). "The hypomethylating agents 5-azacytidine and decitabine show efficacy in myeloid neoplasms such as AML, and the response rate to these drugs appears to correlate with TET2, IDH1/2, and/or DNMT3A mutations." (PMID 33292562, 2020).